PPARG (peroxisome proliferator activated receptor gamma)
Diseases named in the same sentence as PPARG in open-access papers (continued):
Sharing a sentence is not in itself a finding about the gene and the disease.
prostate carcinoma (continued). "From pre-clinical data on prostate cancer, PPARγ agonists may be acting, in part, by inhibiting transactivation of androgen-responsive genes: Peroxisome proliferator-activated receptor γ agonists may down-regulate prostate-specific antigen expression in human prostate cancer." (PMID 30424016, 2018). "Therefore, the role of PPARγ in prostate cancer development may vary depending on the expression levels of other tumor suppressors and proteins that control tumor growth." (PMID 29181019, 2017). "While some clinical observations show that PPARγ expression levels are high in advanced prostate cancer (APC) tissues, ovarian, prostate and testicular carcinoma tissues, it is unclear whether the high levels of PPARγ correlate with favorite outcome in cancer patients." (PMID 28948004, 2017). "Thus combining current results with those of the past suggested that FABP5 and PPARγ may be functioning in a coordinated manner to promote the malignant progression of human prostate cancer cells." (PMID 26814431, 2016). "However, we observed a lack of association between the PPARG Pro12Ala polymorphism and prostate cancer risk in our population." (PMID 26788504, 2015). "Thus, PPARG seems to lose its repression role in prostate cancer." (PMID 19640296, 2009). "Thus,PPARγ is expressed in prostatecancer and activation of PPARγ mightoffer an additional therapeutic option for treatment of prostate cancer in thenear future." (PMID 18483618, 2008). "The study validated two key PPARγ target genes, PRKCZ and PGK1, which were repressed upon PPARγ activation by its natural ligand, 15d-PGJ2, in three prostate cancer cell lines." (PMID 39065726, 2024). "PPARG overexpression also induces the upregulation of AKT3 and triggered mitochondrial ATP synthesis, contributing to prostate cancer progression with elevated energy supplies." (PMID 37932808, 2023). "According to the binding potential of our results and the PPARG antagonistic effects of Tanshinone IIA in other study, Tanshinone IIA can probably acted as a PPARG antagonist in the inhibition of prostate cancer growth." (PMID 37932808, 2023). "Similar phenomena are reported in prostate cancer, showing that FABP5 activates PPARγ and up-regulates VEGF29." (PMID 37416772, 2023). "PPARG activates lipid signaling pathways, and high levels of PPARG/FASN confer a poor prognosis in prostate cancer." (PMID 35874705, 2022). "Therefore, PPARγ antagonists could be used to treat prostate cancer." (PMID 36358965, 2022). "Therefore, increased levels of PPARγ may promote the growth of advanced prostate cancers." (PMID 36175875, 2022). "Silencing PRRT3-AS1 upregulates the expression level of PPARG/PPARγ (peroxisome proliferator activated receptor gamma) that, in turn, inhibits MTOR signaling, leading to autophagy induction and a decrease in viability and survival of prostate cancer cells." (PMID 35317831, 2022). "Some similarities with the prostatic carcinoma also exist, as both frequently express TGFα, EGFR, and peroxisome proliferator-activated receptor gamma (PPARγ)." (PMID 33114321, 2020). "The current literature on the functions of NRs in prostate cancer indicate that DAX1, SHP, RARβ/γ, FXRs, LXRs, VDR, ERβ, ERRβ/γ, and MR can play antioncogenic roles, while PPARγ, RORγ, SF-1, LRH-1, Erα, and GR, as well as AR, can play oncogenic roles." (PMID 31212954, 2019). "A recent study has suggested that the PPARγ antagonist GW9662 also regulates AR signaling within AR-positive, castration-sensitive prostate cancers." (PMID 29181019, 2017). "Therefore, AR-PGC-1α crosstalk may compromise PPARγ function within prostate cancers." (PMID 29181019, 2017). "Androgen-independent prostate cancer cell line PC3-M, expressing high levels of FABP5 and PPARγ was an extremely malignant and metastatic cell line." (PMID 28415688, 2017).
prostate carcinoma (continued). "Recently, it has been reported that activated PPARγ is able to reduce invasion and motility through CXCR4 downregulation in colon, lung and prostate cancer cells." (PMID 27556298, 2016). "Several network measures ranked PPARG and CTGF in the 1st percentile of possible targets on the prostate cancer (PC3) tissue." (PMID 26615774, 2015). "Although 6-iodolactone induces apoptosis in prostate cancer cell lines, the anti-proliferative actions of I2 do not appear to be mediated by PPARG in androgen-independent cells." (PMID 40869121, 2025). "In prostate cancer, for instance, the binding of PEDF to PEDF-receptor/phospholipase A2 at the plasma membrane leads to the upregulation of Peroxisome Proliferator-Activated Receptor Gamma (PPARγ)." (PMID 40001923, 2025). "In terms of cancer metastasis, ROSI activates PPARγ and inhibits the activation of the PI3K-Akt pathway by inhibiting downregulation of CXCL12-induced migration and invasion on the CXCL12/CXCR4 axis in prostate cancer cell lines." (PMID 37251321, 2023). "PPARG is one of three members of the PPAR family of transcription factors that influence the function of serine/threonine kinase 3, which can lead to a more aggressive disease phenotype in prostate cancer." (PMID 34970420, 2021). "Troglitazone induced the expression of PPARγ in the nucleus of PC3 but not LNCaP prostate cancer cells." (PMID 32365809, 2020). "PPARα and PPARβ/δ expressions are detected among normal prostate, BPH, and prostate cancer tissues, while expression of PPARγ was observed in prostate cancer but not in normal prostate and BPH." (PMID 31212954, 2019). "Positive correlation between PPARγ and fatty acid synthase (FASN) protein in prostate cancer cell lines and synergism between TZDs and FASN blockers could be shown in prostate cancer cell viability reduction and apoptosis induction." (PMID 30424016, 2018). "Previous studies showed that γ- and δ-Tocopherol but not α-Tocopherol prevented mammary and prostate cancer by activating PPARγ in animal models." (PMID 29221176, 2017). "Data also suggest that a second member of the nuclear receptor superfamily, the peroxisome proliferator activated receptor gamma (PPARγ), is a tumor suppressor that regulates growth of normal prostate and prostate cancers." (PMID 29181019, 2017). "Together, these results indicate AR may enhance prostate cancer growth and survival by suppressing the induction of FABP4 by PPARγ." (PMID 29181019, 2017). "While PPARγ ligands suppress AR activation in AR-positive, castration-sensitive prostate cancers via mechanisms that are independent of PPARγ, ligand-induced activation of PPARγ increases AR signaling in AR-positive, castration-resistant prostate cancer cells." (PMID 29181019, 2017). "Different TZDs may act by different mechanisms; while CIGLI downregulated cyclin D1 and upregulated p21 by PPARγ independent pathways, ROSI used PPARγ signaling to induce these effects in androgen-independent prostate carcinoma cells." (PMID 25866814, 2015). "Thus, the CRABP-II promoter harbors a consensus RARE, the expression of FABP4 is directly regulated by PPARγ in adipocytes, and, as shown here, FABP5 is a direct target gene for PPARβ/δ in prostate cancer cells." (PMID 20847935, 2010). "The identification of syndecan-1 asa target gene for PPARγ in the breast and prostate cancer cellswas a novel but not unexpected finding." (PMID 18769551, 2008). "The effects of peroxisome proliferator-activated receptor gamma (PPARγ) in lipid metabolism, adipocyte differentiation, and apoptosis have been shown to be augmented by MYC inhibition, resulting in more well-differentiated phenotypes in both prostatic carcinoma and other neoplasms." (PMID 40422212, 2025).
prostate carcinoma (continued). "Although it has been suggested that the increased FABP5 may interact with the increased level of PPARγ in a coordinated way to facilitate malignant progression of prostate cancer cells, the exact role of PPARγ in tumorigenicity of prostate cancer is not clear." (PMID 26814431, 2016). "Because PPARγ activation may have a dual effect on prostate cancer, results derived from cellular studies should be carefully interpreted and clinical trials in humans are pivotal to elucidate the roles of different TZD compounds in the development or prevention of prostate cancer." (PMID 37560306, 2023). "Also overexpression of AKR1C3 could result in the accumulation of prostaglandin F2α (PGF2α), which can not only promote prostate cancer cell 's proliferation but also could enhance prostate cancer cells resistance to radiation and activated the MAPK pathway and inhibited the expression of PPARγ." (PMID 27385003, 2016). "Although androgen can mediate the upregulation of VEGF expression in androgen-dependent prostate cancer cells through the Sp1/Sp3 binding site in the VEGF core promoter, it was not previously known how PPARγ exactly up-regulated VEGF in prostate cancer cells." (PMID 26814431, 2016). "Set against these findings, the Evans team used a prostate cancer, the TRAMP model, to demonstrate that Pparγ heterozygote mice have no change in diseaseprogression compared to wild-type litter mates." (PMID 18528521, 2008).
Alzheimer disease (132 papers, 2006 to 2026). A progressive, neurodegenerative disease characterized by loss of function and death of nerve cells in several areas of the brain leading to loss of cognitive function such as memory and language. "PGC-1α is a coactivator participating in PPARγ transcription and decreased expression is thought to be linked to Alzheimer’s disease." (PMID 40364401, 2025). "The compelling results from animal models of Alzheimer's disease underline the beneficial effects of PPARγ agonists on attenuating Aβ pathologies for future therapies." (PMID 30420872, 2018). "Recently, activation of the retinoid X receptor (RXR), which forms a heterodimer with PPARγ, was implicated as a promising therapeutic treatment for Alzheimer’s disease." (PMID 24889886, 2014). "It is known as a unique angiotensin II receptor blocker with PPARγ agonistic properties, and it was predicted to be associated with Alzheimer’s disease in our study." (PMID 25356910, 2014). "Specifically, the PPARγ agonist, rosiglitazone, improves cognition and protects from neuropathology associated to Alzheimer’s disease in transgenic mouse models and in humans." (PMID 24223732, 2013). "The influence of genetic mutations on the course or overall risk of Alzheimer`s disease have almost only be addressed for the PPARγ2Pro12Ala polymorphism, albeit a change in PPARγ activity by this mutation will most likely affect the adipose tissue." (PMID 22654722, 2011). "The compelling results from animal models of Alzheimer’s disease underline the beneficial effects of PPARγ agonists for future therapies." (PMID 22654722, 2011). "Nonsteroidal anti-inflammatory drugs (NSAIDs) have been considered to delay the onset and reduce the risk to develop Alzheimer's disease, while they also directly activate PPARγ." (PMID 18645613, 2008). "For the selection of SNPs in the PPARG gene, we were also interested in those reported as potentially clinically relevant, as observed for the rs1151999 SNP that was associated with protection against Alzheimer’s disease." (PMID 37047733, 2023). "However, evidence suggests that targeting PPARγ and/or PPARδ can improve memory deficits and/or the pathology associated with Alzheimer’s disease in rodent models." (PMID 37190025, 2023). "The reduced risk associated with pioglitazone may also result from the regulation of PPARγ on genes associated with Alzheimer’s disease." (PMID 31085804, 2019). "Knockdown of the PPARγ gene may also affect the expression of several other genes associated with Alzheimer’s disease." (PMID 31085804, 2019). "PPARγ may also be associated with Alzheimer disease (AD) since activation of PPARγ decreases the release of amyloid-β (Aβ), main component of the amyloid plaques associated with AD." (PMID 19390629, 2009). "Indeed, in a replication study PPARγ was foundto be significantly associated with Alzheimer's disease." (PMID 18645613, 2008). "Knockdown of the PPARγ gene affects the expression of several genes associated with Alzheimer’s disease, suggesting that pioglitazone may regulate the transcription of genes related to Alzheimer’s disease and may potentially affect the risk of dementia." (PMID 30262775, 2018). "This intervention appeared to protect against the onset of Alzheimer’s disease and slow its progression, potentially through pathways involving peroxisome proliferator-activated receptor gamma (PPARγ)." (PMID 41149774, 2025). "Peroxisome proliferator-activated receptor gamma (PPARγ) is a nuclear receptor known to play a critical role in regulating neuroinflammation and neurodegenerative processes, including Alzheimer’s disease." (PMID 41039514, 2025). "Several animal models of PD, HD, and Alzheimer’s disease (AD) have shown a neuroprotective effect of PPARγ activation by agonists." (PMID 36834679, 2023). "Recently, PPARγ has also been proposed as a therapeutic target for ovarian cancer and Alzheimer Disease (AD)." (PMID 36176461, 2022).
Alzheimer disease (continued). "Another beneficial interaction was found between peroxisome proliferator-activated receptor gamma (PPARγ) and CBD, which was associated with neuroprotective properties in ischemic stroke and with stimulated neurogenesis in a model of Alzheimer’s disease." (PMID 35631322, 2022). "Bis(ethylmaltolato)oxidovanadium (IV) (BEOV) ameliorates ER stress and neuronal apoptosis by regulating PPARγ in mouse Alzheimer’s disease models." (PMID 35739990, 2022). "PPARγ agonists have been proven to be neuroprotective in vitro and in vivo models of Alzheimer’s disease (AD)." (PMID 36217155, 2022). "Through PPARγ modulation, this neolignan exerts anti-inflammatory actions in animal models of acute lung injury, ulcerative colitis, and Alzheimer’s disease, as well as cardioprotective effects, and beneficial properties in metabolic disorders." (PMID 33498245, 2021). "Recently, several researches have shown that activating PPARγ signaling leads to a reduction in inflammation which is related to regulation of the M1/M2 phenotype in Alzheimer's disease and experimental stroke." (PMID 33688509, 2021). "To date, PPARγ has been a focal point in the modulation of neuro-inflammation for Alzheimer’s disease (AD)." (PMID 34833044, 2021). "Activating the PPARγ signaling pathway has a protective function as it reduces neuroinflammation in several diseases (i.e., Alzheimer's disease, Parkinson's disease, and stroke)." (PMID 33688509, 2021). "The neuroprotective effect of CBD through the activation of PPARγ was observed in an experimental study of Alzheimer’s disease." (PMID 33171772, 2020). "In conclusion, the data obtained from these studies underline the implication of PPARγ in the anti-inflammatory effects of CBD, in experimental models of Alzheimer’s disease, Ischemic stroke, Parkinson’s disease and EAE disease." (PMID 33171772, 2020). "A similar improvement of PPARγ expression has been previously reported for OC-rich EVOO in the brain of Alzheimer’s disease mice model, and for the EVOO simple phenol hydroxytyrosol, a precursor of OA, in TNF-α-stimulated SGBS cells." (PMID 31766503, 2019). "PPARγ also plays a beneficial role in neurodegenerative disorders such as Parkinsonism, amyotrophic lateral sclerosis, Alzheimer’s disease and brain injury, and ocular diseases." (PMID 31018521, 2019). "The down-regulation of PPARγ has gained increasing attention in neuroinflammation of Alzheimer’s disease (AD)." (PMID 27287266, 2016). "Inflammation contributes to many neurodegenerative diseases, including Alzheimer's disease and Parkinson's disease, and indeed PPARγ activation has shown beneficial effects in many animal models." (PMID 26713087, 2015). "In recent years, the neuroprotective effects of PPARγ agonists has been assessed in several in vitro and in vivo models of several neurodegenerative conditions including PD, Alzheimer’s disease, cerebral ischemia and amyotrophic lateral sclerosis." (PMID 25007880, 2015). "Here we have demonstrated off-target binding of Bexarotene to PPARγ, also a target that has emerged for the treatment of Alzheimer's disease." (PMID 26451138, 2015). "Several groups have observed that prolonged treatment with PPARγ agonists can reduce Alzheimer’s disease pathology, demonstrating its potential therapeutic efficacy." (PMID 24889886, 2014). "Our findings are in agreement with the effects observed with PPARγ agonists in models of ischemic and hemorrhagic stroke, and CNS disease including Alzheimer's disease, multiple sclerosis, amyotrophic lateral sclerosis and Parkinson's disease." (PMID 24603727, 2014). "Among the potential repositioning drugs, peroxisome proliferator-activated receptor-γ (PPARγ) agonists and angiotensin receptor blockers have been spotlighted for Alzheimer’s disease." (PMID 25356910, 2014).